FAP (fibroblast activation protein alpha)
Diseases named in the same sentence as FAP in open-access papers (continued):
Sharing a sentence is not in itself a finding about the gene and the disease.
tumor (continued). "Immunohistochemical analysis of metastatic nodules in both lung and liver tissues from CRC and PDAC tumor‐bearing mice showed that metastases in Bmal1−/− mice were enriched in stromal fibroblasts that were positive for FAP, α‐SMA, DESMIN, PDGFRα, and PDGFRβ." (PMID 37330661, 2023). "FAP-targeted CAR-T cells demonstrated enhanced antitumor response when combined with other immune therapies, including tumor-associated-antigen (TAA) CAR-T or vaccine." (PMID 37046312, 2023). "Similar to the subcutaneous tumours, comparable patterns were observed for the autoradiography and FAP-IHC density maps in the orthotopic tumours." (PMID 37408254, 2023). "Co-injection with an excess DTPA-700DX-MB reduced uptake, and autoradiography correlated with FAP expression in the stromal tumour region." (PMID 37408254, 2023). "A longer blood retention would prevent fast binding of the bispecific tracers to their targets: PSMA in the LNCaP tumor xenografts and FAP in the HEK293T:hFAP tumor xenografts." (PMID 36770755, 2023). "The stromal cells along with tumor cells release a host of immunosuppressive cytokines including TGF-β, IL-10, ARG-1, inducible nitric oxide synthase, COX2, PGE2, FAP, and PD-L1 to help the tumor evade CAR T cells." (PMID 37509394, 2023). "Numerous studies have also been carried out on the treatment of CAFs, but most of these studies are in the preclinical stage, and clinical trials on CAFs and tumors mostly focus on tumor PET imaging of FAP (molecular markers of CAFs)." (PMID 37666813, 2023). "This is accompanied by an increase in intra-tumor CD8+ FAP(hF1) UCAR T-cell levels and a substantial reduction in tumor growth, consistent with loss of tumor-supportive CAFs." (PMID 37251405, 2023). "In all DF samples, the tumor and stromal cell FAP intensity scores were 3 and FAP density scores were >75%." (PMID 37333052, 2023). "In STS NOS and cFS, less than half of the tumors showed a FAP positivity over 50% of the tumor cells (score 0)." (PMID 37727209, 2023). "Overexpression of FAP enhanced the tumor-promoting and EMT-inducing effects of stromal fibroblasts, while knockdown of FAP weakened those effects." (PMID 37461061, 2023). "Targeting FAPα using small-molecule 18F-labeled inhibitors (FAPIs) has recently garnered significant attention for non-invasive tumor visualization using PET." (PMID 38140090, 2023). "The results showed that this DNA vaccine stimulated immune response and promoted CD8+ T cell activity against tumor stromal cells expressing FAP." (PMID 37316886, 2023). "The probe was constructed with the clinically validated cyclic peptide FAP-2286, which has high tumor uptake and retention, and the FDA-approved ICG." (PMID 38026901, 2023). "It was shown that the eNVs-FAP vaccine effectively inhibited tumor growth in mouse models of lung cancer." (PMID 37641132, 2023). "Taken together our results indicate that FAP(hF1) UCAR T-cell treatment of tumor-bearing mice results in significant FAP+ cells depletion and reduction in stromal physical barrier in the tumor microenvironment, confirming their onsite anti-CAF activity." (PMID 37251405, 2023). "Experimental evidence has indicated that FAP-expressing stromal cells contact T cells at the outer edge of the tumor and restrict the proliferation and intratumoral recruitment of effector T cells in various cancers." (PMID 35951090, 2023). "Two novel 68Ga-labeled pyridine-based FAP-targeted tracers were successfully synthesized and evaluated using a preclinical tumor model." (PMID 36986548, 2023). "There was a very low tumor uptake in mice injected with [68Ga]Ga-HTK03041, showing very minimal FAP expression in this tumor model." (PMID 36770755, 2023). "Although pre-treatment of FAP-CAR T cells followed by anti-PD-1 therapy showed enhanced inhibition of PDAC tumor growth, the overall survival was only modestly improved, thus warranting investigation of other combination therapies." (PMID 37607999, 2023).
tumor (continued). "This system allows tumor-restricted expression of FAP-BiTE, which elicits potent T-cell cytotoxicity against CAFs in human biopsies (malignant ascites and prostate cancer tissue)." (PMID 36708970, 2023). "The area of FAP-positive tumor tissue was similar in all species (p > 0.8990) with a relative stained area of 30.6%, 33.0%, and 42.2% in canine, feline, and human STSs, respectively." (PMID 37727209, 2023). "We first confirmed the existence of POSTN+FAP+ eCAF subpopulations in tumour tissues of GC patients and in the TCGA database." (PMID 37199594, 2023). "By the ESTIMATE algorithm, patients in high-FAP yielded a lower tumor purity than those in low-FAP groups, revealing a complicated and abundant stromal was involved in those patients." (PMID 37046312, 2023). "The in vivo distribution and metabolic characteristics of [68Ga]Ga-FAP-2286-ICG in U87MG tumor-bearing mice were evaluated in real-time and noninvasively via PET/CT imaging at 30, 60 and 90 min post-injection of the radiotracer." (PMID 38026901, 2023). "Overexpression of the target structure in the neoplastic tissue samples is crucial to achieving a specific accumulation of targeted dyes in the tumor, and FAP is among the list of potential candidates." (PMID 37727209, 2023). "The use of an orthogonal marker to EpCAM, which we present to be FAP, allows for better disease staging and monitoring of the tumor response to treatment even if EpCAM is downregulated." (PMID 37759489, 2023). "FAP’s constrained expression combined with its role in invasion and tumor metastasis, makes it a promising target for developing FAP-targeted radiopharmaceuticals for the imaging and therapy of carcinomas." (PMID 37375746, 2023). "We examined the DEGs in PanCK(+) tumor epithelial cells adjacent to FAP(+) CAFs areas at the tumor invasive margin between EOCC (n = 12 AOIs) and LOCC (n = 12 AOIs) using NGDSP analysis." (PMID 37964075, 2023). "Other preclinical studies of anti-FAP CAR T-cells derived from other mAb clones report significant anti-tumor activity in 4T1 and other solid tumor models, with no on-target/off-tumor toxicities." (PMID 38201551, 2023). "This explains why, already in the first metastasis, FAP is significantly reduced compared to the primary tumor." (PMID 37892020, 2023). "QRT-PCR as well as western blotting demonstrated that the concentrations of FAP transcripts and proteins were much higher in tumor tissues than in their adjacent healthy tissues." (PMID 37752545, 2023). "In clear renal cell carcinoma, FAP overexpression correlates with tumor aggressiveness and poor survival." (PMID 37316886, 2023). "Results showed that FAP was up-regulated in gastrointestinal cancers and involved in tumor cell mobility, macrophages infiltration as well as M2 polarization process." (PMID 37325617, 2023). "A DNA vaccine directed against FAP suppressed tumor proliferation by stimulating a CD8+ T-cell-mediated immune response." (PMID 36672284, 2023). "In the evaluation of the percentual expression of FAP in the two different tumor cores on the TMA, a deviation of more than 5% was detectable in 29 CRC cases (43%)." (PMID 37614665, 2023). "They found that immature CAFs showed higher expression of CAF markers, including FAP, and immature CAFs in the tumor stroma promoted epithelial to mesenchymal transition." (PMID 37316886, 2023). "Conversely, forced overexpression of FAP significantly promotes NK cell invasion through matrix in both transwell and tumor spheroid assays, ultimately enhancing tumor cell lysis." (PMID 38196606, 2023). "Compared to 2D-4-culture, a greater proportion of CD163 + and FAP + cells were exhibited in 3D-4-culture, similar to what occurs with tumor infiltration in HNSCC as well as a notable increase in the passage of HUVECs through compartments." (PMID 37907991, 2023). "For HIF1A, ETS1, and VEGFR2, we detected significant protein levels in FAP-overexpressing tumor samples." (PMID 36672341, 2023).
tumor (continued). "Promisingly, we found a combination of FAP-CAR T cells followed by Meso-CAR T cells had a more robust effect with tumor stabilization and even regression observed in some PDAC-bearing mice that translated into greater prolongation of survival." (PMID 37607999, 2023). "Using OVs to express and release biTEs in the local tumor environment can be a successful way to overcome potential off-target safety concerns as seen in anti-FAP CAR-T cell strategies." (PMID 38022679, 2023). "FAP overexpression has been demonstrated in most of the epithelial cancers, especially in tumours with a high degree of desmoplasia." (PMID 37608378, 2023). "Genetic deletion and pharmacological inhibition of FAP inhibited tumor growth in an endogenous mouse model of lung cancer driven by the K-rasG12D mutant." (PMID 36672284, 2023). "Fibroblast Activation Protein (FAP) + CAFs were extracted from tumor tissue, treated with 10 μM Curcumin, and co-cultured with corresponding PBMCs." (PMID 38008819, 2023). "Collectively, these data demonstrate that FAP-CAR T cells enhanced the efficacy of anti-PD-1 therapy in controlling tumor growth." (PMID 37607999, 2023). "In a study, a nanovesicle was designed by engineering tumor cell-derived exosomes with the fibroblast activation protein-α (FAP) gene, with the purpose of serve as a tumor vaccine and to overcome the immunosuppressive characteristics of TME." (PMID 37915578, 2023). "The peptide showed advantages in terms of tumor-to-background ratios, besides tumor-to-kidneys, but its tumor uptake was FAP expression-dependent." (PMID 37261473, 2023). "Overexpression of FAP in tumors has been shown to promote tumor growth, angiogenesis, and metastasis." (PMID 36986548, 2023). "In animal models, fibroblast activation protein (FAP)-targeted CAR-T cell therapy showed a reduction in tumor fibroblasts by increasing the cytotoxic function." (PMID 37420216, 2023). "More robust inhibition of tumor growth and more prolonged survival was observed in tumor-bearing mice treated with FAP-CAR T cells." (PMID 37607999, 2023). "FAP expression was evaluated in the tumor center and margin in 449 CRC tissue samples by IHC in another research." (PMID 37316886, 2023). "Fibroblast activation protein (FAP), a protein of the tumour microenvironment, is overexpressed in a wide range of cancers which makes it an attractive target for both tumour imaging and therapy." (PMID 37608378, 2023). "Exemplary monoclonal antibodies against FAP have shown an inhibition of tumor progression in mouse models of head, neck, lung, and pancreatic cancer." (PMID 37686288, 2023). "The FAP aptamers screened in this study provide a promising direction for the development of rapid tumor diagnosis and targeted therapy." (PMID 36838669, 2023). "Other preclinical studies have demonstrated that pharmacological inhibition or deletion of FAP-positive CAFs results in the attenuation of tumor growth and increased survival in pancreatic cancer models." (PMID 37099374, 2023). "FAP is overexpressed in the stromal fibroblasts of most epithelial malignancies, and it can be used as a potential target for tumor diagnosis and treatment." (PMID 36838669, 2023). "We found significantly positive Pearson R values for the majority of tumor entities, especially regarding correlations between FAP and the angiogenesis-related genes FLT1, KDR, HIF1A, and ETS1." (PMID 36672341, 2023). "The long circulation time of FAP-targeting antibodies and poor tumor retention time of FAP-targeting small molecules used to be a matter of concern." (PMID 36813980, 2023). "Specifically, FAP-CAR T cells were often observed directionally migrating along remodeled thinner collagen fibers within the tumor nests." (PMID 37607999, 2023). "Fluorescence images of all three HNC tumor-bearing mice at 72 h after injection of [68Ga]Ga-FAP-2286-ICG were generally consistent with the findings on the corresponding PET/CT images." (PMID 38026901, 2023).
tumor (continued). "Fibroblast activation accompanied by the upregulation of the FAP gene appears to significantly contribute to tumor progression and metastasis." (PMID 36825204, 2023). "In this study, we aimed to establish (for CXCR4) and evaluate (for FAP) a workflow demonstrating the utility and applicability of ML in the field of theranostics—by predicting ligand-related tumor microenvironments for other potential target structures." (PMID 36672341, 2023). "Consistent with tumor suppression, pharmacological inhibition of TGF‐βR1 abrogated Bmal1‐deletion–triggered tumor fibrosis that showed reduced positive structures of FAP, α‐SMA, DESMIN, PDGFRα, and PDGFRβ." (PMID 37330661, 2023). "Sequential treatment inhibited the growth of the tumor more than those in the FAP + FAP group (p < 0.05), as well as those in the CLDN18.2 + CLDN18.2 group (p < 0.01)." (PMID 37046312, 2023). "Thirty-three human (33/39, 85%), 40 canine (40/53, 76%), and 22 feline (22/24, 92%) STSs showed FAP expression in over 10% of the tumor cells." (PMID 37727209, 2023). "High FAP expression was associated with shorter survival in KIRP and KIRC, potentially attributed to variations in primary tumor location." (PMID 37490719, 2023). "The serum FAP level, the number of nodules, tumor size, liver function, extrahepatic metastasis, and history of anti-tumor therapy were all significantly different between the two groups before PSM analysis." (PMID 37254146, 2023). "Given the close relationship of FAP and angiogenesis-related genes, we finally looked at endothelial cell content in TCGA tumor specimens." (PMID 36672341, 2023). "FAP inhibitors (FAPIs) can be used as radioactive compound carriers delivered specifically to the tumor area." (PMID 36899938, 2023). "Unique to the CTC assay was the co-isolation of epithelial CTCs (EpCAM) and mesenchymal CTCs (FAPα), which better recapitulated the complex tumor microenvironment compared with using epithelial CTCs only." (PMID 37759489, 2023). "The correlation between tumor volume and blood FAP levels suggests potential utility in guiding treatment strategy selection." (PMID 37864148, 2023). "The biodistribution of 177Lu-FAP-2287 was evaluated in vivo by SPECT/CT imaging following a single dose of 30 MBq 177Lu-FAP-2287 in MCA205-mFAP tumor bearing mice (n = 6)." (PMID 37086273, 2023). "We found that PTX significantly reduced primary tumor size and increased the percentage of pan-CK+/FAP+ hybrid cells." (PMID 37607007, 2023). "After intravenous injection, both 64Cu radiolabeled αFAP TMs specifically accumulated at the site containing FAP-expressing tumor cells (green circles)." (PMID 38102692, 2023). "Immunosuppressive checkpoint proteins or cytokines expression, microsatellite instability and tumor mutational burden analysis also indicate the regulation role of FAP in tumor progression." (PMID 37166418, 2023). "A series of experimental models were established to investigate the effects of FAP on immune suppression and tumor progression in GBM therapy in vitro and in vivo, and PT100, a small molecule inhibitor of FAP, was also evaluated for the treatment of GBM." (PMID 36382346, 2023). "The binding and migration ability of the probe was assessed using the FAP transfected tumor cell line." (PMID 36879039, 2023). "The ceRNA network is also constructed and identified the involvement of LINC00707/hsa-miR-30e-5p/FAP, LINC02535/hsa-miR-30e-5p/FAP, LINC02535/hsa-miR-30d-5p/FAP, as well as AC026356.1/hsa-miR-30d-5p/FAP axis in tumor progression." (PMID 37166418, 2023). "In LIHC, IHC staining suggested that more M2 macrophages were presented in tumor tissues of patients with high FAP expression." (PMID 37325617, 2023). "A nanosystem delivering FAP antibodies can inactivate CAF by downregulating the expression of CXCL12 to modulate the tumor microenvironment of PCa." (PMID 37784082, 2023).
tumor (continued). "According to the authors, FAP-2286 offered an attractive profile for TRT due to its good tumor uptake and retention in FAP-positive tumors." (PMID 36813980, 2023). "In this study, we used a BALB/c nude mouse model subcutaneously injected with a human‐derived GBM cell line to investigate the effect of FAP on tumor invasiveness and observe the therapeutic effect of PT100 on subcutaneous tumors." (PMID 36382346, 2023). "In FAP+ tumor cells, compared to Nb-BiTE and Nb-TriTE + hPD-1 group, Nb-TriTE group led to significant cell divisions." (PMID 38031188, 2023). "Inhibition of tumor angiogenesis and subsequent suppression of mouse pancreatic tumors was also observed after removal of FAP+ CAFs in FAP-targeted chimeric antigen receptor (CAR) T cells." (PMID 37254126, 2023). "After a single intravenous dose, [177Lu]Lu-FAP-2286 had a high anti-tumor activity in HEK-293 xenografts that expressed the FAP receptor." (PMID 36813980, 2023). "Recently, FAP-targeted radiopharmaceuticals are widely used in clinical research and achieved great results in tumour imaging." (PMID 37608378, 2023). "To summarize, FAP(+) CAFs as well as EPCAM(+) tumor epithelial cells show an upregulation of WNT signaling." (PMID 37964075, 2023). "Novel hetero-bivalent radiolabeled antibodies to FAP and prostate-specific membrane antigen (PSAMA) are being developed, having demonstrated high and specific tumor targeting of FAP and PSMA." (PMID 37046676, 2023). "The proposed mechanism of action of this drug is that it targets IL-2 to FAP expressing tumor stroma, thereby limiting on-target, off-site toxicities associated with IL-2 cytokine therapy." (PMID 38196606, 2023). "We also compared gene expression profiles of FAP(+) CAFs at tumor invasive margins between EOCC (n = 12 AOIs) and LOCC (n = 12 AOIs)." (PMID 37964075, 2023). "A brown-stained region surrounding the tumor cells was revealed by FAP staining, with some exhibiting streak-like structures that indicate fibroblasts expressing FAP." (PMID 38026901, 2023). "Depletion of FAP-positive stromal cells with the FAP-targeted immunotoxin αFAP-PE38 reduced the recruitment of tumor-infiltrating immune cells in the tumor microenvironment and inhibited tumor growth." (PMID 37963845, 2023). "In clinical practice, due to the existence of abundant new vessels in tumor, a correlation that avoided the interference from blood background was meaningful to FAP imaging." (PMID 36986521, 2023). "We have shown that the subcutaneous PDAC299 tumours have an abundant stroma with collagen bundles containing FAP-expressing fibroblasts." (PMID 37408254, 2023). "FAP expression was significantly lower in tumor tissues of CESC, SKCM, KICH, THCA, UCEC, and UCS compared to their respective matched-normal tissues." (PMID 37490719, 2023). "Firstly, tumor cells and tumor tissues were tested for FAP and PD-L1 expression by flow cytometry and public datasets showed that their variable expression levels." (PMID 38031188, 2023). "177Lu-FAP-2287 rapidly accumulated in MCA205-mFAP tumors leading to significant tumor growth inhibition (TGI) and longer survival time." (PMID 37086273, 2023). "A dramatic decrease in the CAFs measured by immunostaining was observed in the FAP-mBBZ group, while CAFs were abundant in tumor lesions of the CLDN18.2-mBBZ CAR-T and UTD groups." (PMID 37046312, 2023). "In NSCLC, FAP+aSMA+CAFs, which prevent T-cell contact with tumour cells, are also characterized by high expression levels of POSTN." (PMID 37199594, 2023). "Other studies have identified other fibroblasts with a high expression of CD146, α-SMA, FAP and Meflin, that exhibit tumor suppression or promotion tendencies." (PMID 37344903, 2023). "Their further investigations lead to significant findings that the proteolytic activity of FAP participates in matrix degradation, but other functions of the protein stimulate increased tumor growth." (PMID 37111277, 2023).